C14orf93 (chromosome 14 open reading frame 93)
Synonyms: FLJ12154; RTFC
Tractability: Antibody: UniProt places it where antibodies can reach, with high confidence; UniProt predicts a signal peptide or a membrane-spanning region; its Gene Ontology location is reachable by antibodies, with medium confidence; the Human Protein Atlas places it where antibodies can reach. PROTAC: UniProt records ubiquitination sites on it; ubiquitination databases record sites on it.
Gene: Protein-coding gene on chromosome 14 (22,985,894 to 23,010,529, reverse strand). Ensembl gene ENSG00000100802.
Subcellular location: Secreted
Subcellular location (Human Protein Atlas): Nucleoplasm; Plasma membrane; Predicted to be secreted
Gene Ontology:
Molecular function: protein binding; RNA binding
Cellular component: extracellular region
Genetic constraint (gnomAD): Loss-of-function variants: 23 observed, 44.42 expected, observed/expected ratio (o/e) 0.52, 90% interval 0.37 to 0.73. The upper end of that interval is the gene's LOEUF score, 0.73, which puts it in group 3 of 6, group 1 being the genes least tolerant of losing a copy. Missense variants: 579 observed, 704.02 expected, observed/expected ratio (o/e) 0.82, 90% interval 0.77 to 0.88. Synonymous variants: 253 observed, 277.38 expected, observed/expected ratio (o/e) 0.91, 90% interval 0.82 to 1.01.
Homologues: Orthologues: chimpanzee C14H14orf93 (99% identical), macaque C7H14orf93 (98% identical), dog C14orf93 (92% identical), guinea pig C14orf93 (92% identical), rabbit C14orf93 (92% identical), pig C14orf93 (92% identical), rat C15h14orf93 (88% identical), mouse 4931414P19Rik (87% identical), tropical clawed frog c1h14orf93 (38% identical).
Diseases named in the same sentence as C14orf93 in open-access papers:
C14orf93 is named in the same sentence as 6 diseases in open-access papers, as found by Europe PMC text mining. Sharing a sentence is not in itself a finding about the gene and the disease. The quoted sentences say what the papers report.
lymphoma (1 paper, 2011). A malignant (clonal) proliferation of B- lymphocytes or T- lymphocytes which involves the lymph nodes, bone marrow and/or extranodal sites. "Of particular interest for future investigation are the two previously uncharacterised genes, c14orf93 and ZBTB44, both of which are differentially expressed in lymphoma-derived cell lines." (PMID 21887344, 2011). "Four antigens, TCEB3, BECN1, c14orf93, and ZBTB44, showed more frequent recognition by lymphoma patients' sera." (PMID 21887344, 2011). "However, this does not exclude the possibility that the five antigens preferentially recognised by sera from patients (TCEB3, BECN1, CEP250, c14orf93 and ZBTB44) may have a role in the pathobiology of lymphoma." (PMID 21887344, 2011).
medullary thyroid carcinoma (1 paper, 2017). "Through genetic linkage analysis and exome sequencing, we previously identified an uncharacterized gene C14orf93 (RTFC, mouse homolog: 4931414P19Rik) as a novel susceptibility gene for familial non-medullary thyroid carcinoma, and demonstrated its function in promoting thyroid tumor." (PMID 28230092, 2017).
myeloma (1 paper, 2011). "ZBTB44 and c14orf93 were differentially expressed, with ZBTB44 showing highest expression levels in one B-NHL and two myeloma cell lines and most frequent upregulation (5/9) in cell lines derived from T-cell malignancies." (PMID 21887344, 2011).
T-cell lymphomas (1 paper, 2011). "C14orf93 maps to 14q11.2, which is a translocation hotspot in T-cell lymphomas because the alpha T-cell receptor genes map to this locus." (PMID 21887344, 2011).
cancer (2 papers, 2011 to 2022). A tumor composed of atypical neoplastic, often pleomorphic cells that invade other tissues. "Chromosome 14 open reading frame 93 (C14orf93) gene, also known as RTFC (regulator of thyroid function and cancer), regulates in vitro thyroid differentiation and in vivo thyroid function." (PMID 35295987, 2022).
C14orf93 also shares sentences with these, for which no sentence is quoted: thyroid tumor (1 paper).